CD68 (CD68 molecule)
Diseases named in the same sentence as CD68 in open-access papers (continued):
Sharing a sentence is not in itself a finding about the gene and the disease.
breast carcinoma (continued). "Here, we report the 10-year OS, breast cancer-specific survival (BCSS) and disease-free survival (DFS) rates according to the number of M2 TAMs (CD163+) and all TAMs (CD68+) in a cohort of 278 non-metastatic breast cancer patients, every second of which was HER2+ (n = 139)." (PMID 38339385, 2024). "Also, the immunofluorescence results revealed significantly higher expression of CD68 in IBC than in the non-IBC samples, which reinforces the concept that macrophages release pro-angiogenic factors to drive breast cancer progression in a feedback loop." (PMID 39103878, 2024). "This meta-analysis further supports the clinical significance of TAMs in breast cancer, and both CD68- and CD163-positive TAMs could be prognostic markers in non-metastatic breast cancer." (PMID 31528210, 2019). "Furthermore, we performed a retrospective study and systematic review of the published studies on CD68- and CD163-positive macrophages in non-metastatic breast cancer." (PMID 31528210, 2019). "Immunofluorescence revealed a barely detectable immunostaining of CD68 in CAFs and NHDFs meanwhile no expression can be detected for CD163 and F4/80 markers in CAFs and in NHDFs, ruling out that the cells prepared from breast cancer tissue are not macrophages." (PMID 28178651, 2017). "We also found that CD47 and CD68 expression were more abundant in hormone receptor-negative breast cancer, such as triple-negative breast cancer (TNBC) and HER2 overexpression breast cancer, while the expression density of CD47 and CD68 decreased in luminal-type breast cancer." (PMID 31528120, 2019).
glioma (122 papers, 2010 to 2026). A benign or malignant brain and spinal cord tumor that arises from glial cells (astrocytes, oligodendrocytes, ependymal cells). "Linear regression analysis revealed that the number of CD68‐positive cells was significantly positively correlated with the number of GFAP+PDPN+ cells in glioma, with CD68+CD163+ cells showing a similar association with GFAP+PDPN+ cells." (PMID 38470096, 2024). "Siglec-15 was predominantly expressed on peritumoral CD68+ tumor-associated macrophages, which accumulated to the highest level in grade II glioma and then declined as grade increased." (PMID 37234161, 2023). "Upregulation of CD68 is associated with a higher malignancy in gliomas and poor prognosis for glioma patients." (PMID 34964926, 2022). "CD68 expression is characteristic of tumor-associated macrophages, whose enrichment in glioma has been associated with poor prognosis." (PMID 31649675, 2019). "Indeed, there is a highly significant correlation between the expression of LGALS9 (the gene encoding Gal9) and CD68 (a classical marker of GB macrophages) expression in patient samples from two distinct glioma cohorts." (PMID 40157890, 2025). "Moreover, correlative CD68 IHC demonstrated nominal glioma-associated microglia/macrophage (GAM) expression within the same areas." (PMID 26517124, 2015). "Other studies have similarly demonstrated increased CD68+ cells in the rGBM microenvironment when comparing pre- and post-treatment glioma samples and found it may be associated with decreased efficacy of immune checkpoint inhibitors, such as pembrolizumab anti-programmed cell death 1 (PD-1)." (PMID 39409905, 2024). "SERPINA3 expression displayed a positive association with CD68 and IBA1 in primary gliomas, as evidenced by the data." (PMID 41550507, 2026). "The results displayed that high levels of CD68 mRNA have shorter surviving compared to low expression in glioma patients." (PMID 41550507, 2026). "Intriguingly, within GBM tissues, we further confirmed the expression of SERPINA3 in GAMs, and that SERPINA3 expression is positively associated with CD68 and IBA1 in primary gliomas, indicating remodeling of the tumor immune microenvironment." (PMID 41550507, 2026). "CD68 (pan‐macrophage/microglia) and CD163 (M2‐associated) have been linked to worse outcomes in glioma and are widely used surrogates of TAM burden/polarization." (PMID 41354084, 2025). "Our univariate analysis of CD68+ macrophages in glioma tissues revealed that these macrophages were related to poor survival." (PMID 38415455, 2025). "Statistical analysis revealed a significantly higher abundance of GFAP+LPS+ cells compared to CD68+LPS+ cells in glioma tissues." (PMID 39660865, 2025). "The study revealed that CD68 expression was positively correlated with the malignancy grade of glioma." (PMID 38539537, 2024). "Then, we performed IHC staining analysis for CD68 and CCL2 in an in-house cohort, and the results showed that high BCL2A1 expression was significantly associated with CD68 and CCL2 expression in gliomas." (PMID 37889551, 2023). "We found that Siglec-15 was coexpressed with CD68 in the TAMs localized in peritumoral tissues, and that TAMs accumulated to the highest frequency in grade II glioma but then gradually declined in grade III and IV." (PMID 37234161, 2023). "The content of CD68-labeled GAMs in glioma samples was higher than that in normal brain tissue and positively correlated with glioma grade." (PMID 36969175, 2023). "PTX3 is a component of the glioma microenvironment, being generated by tumor cells and infiltrating CD68-positive macrophages, and local PTX3 levels are correlated with grade and malignancy." (PMID 37091145, 2023). "To further validate our findings, we performed IHC and multiple immunofluorescences staining on two of the TAM markers and found that the expression of BCL2A1 was significantly correlated with CCL2 and CD68, and they were coexpressed in gliomas." (PMID 37889551, 2023).
glioma (continued). "Immunohistochemical staining of the glioma tissue from GBM patients revealed that CD68+ CD206+ M2‐TAMs (mainly referred to as M2‐Mφ) were enriched at the infiltrative margins of glioma." (PMID 37544917, 2023). "For the rat brain cryosections bearing BT4C gliomas, anti-FR-α antibody was used to detect FR-α while the anti-CD68 antibody was selected to detect both activated macrophages and microglia." (PMID 37275898, 2023). "We found that IBA1 and CD68 (markers of macrophages) were significantly upregulated in high cuproptosis group, which confirmed that patients with gliomas in a high level of cuproptosis were characterized by macrophage enrichment." (PMID 37515314, 2023). "The finding of enrichment of CD11c+CD68+ cells (potentially microglia) at the glioma edge is consistent results from a prior study." (PMID 35316217, 2022). "The staining from the HPA dataset and the patient-derived glioma tissues showed that there is a significant number of CD3 positive and CD68 positive cells in all stages of glioma tissue." (PMID 35250490, 2022). "Second, despite similar T cell frequencies in gliomas and brain metastases, glioma T cells preferentially interacted with CD68+p-STAT3– monocyte-derived cells within tumor relative to that observed for brain metastases (P = 0.023)." (PMID 35316217, 2022). "Our immunohistochemistry results are in accordance with a previous study that CD68 expression in lower-grade glioma tissues (LGGs, WHO II and WHO III) was significantly higher than the expression in normal brain tissues." (PMID 35756621, 2022). "The Spearman correlation analysis results suggested that the immune marker sets of Treg (FOXP3, CCR8, TGFβ1), TAM (CCL2, CD68, IL-10), and MDSC (CD33, ITGAM, FUT4) were significantly associated with the PROS1 expression in glioma." (PMID 36685506, 2022). "CD163+ macrophages were evident throughout the TME of metastatic tumors, whereas in gliomas, CD68+, CD11c+CD68+, and CD11c+CD68+CD163+ cell subtypes were commonly observed." (PMID 35316217, 2022). "In human gliomas, TAMs are commonly identified by the expression of a broad monocyte lineage marker CD68 and M2-specific Mφ markers CD163 and CD204." (PMID 36451253, 2022). "From the single-cell data of nine glioma samples, we identified inflammatory cell populations that were positive for CD68." (PMID 35525921, 2022). "The expression of IGF2BP3, YAP1, CD68 (human macrophage marker) was enhanced in circNEIL3-high glioma tissues compared to circNEIL3-low tissues." (PMID 35031058, 2022). "The expression of CD68 was also elevated in high-grade gliomas, suggesting increased total numbers of macrophages in the tumor." (PMID 36266311, 2022). "In glioma patients, CD68+IL-16+ macrophages in the brain tissue have been identified as the major source of IL-16 expression correlating well with the glioma WHO grade and therefore its malignancy." (PMID 34654395, 2021). "We also observed co-expression of BTK with CD163 and CD68 in a proportion of cells from high-grade glioma tissues." (PMID 34645618, 2021). "Further analysis revealed that glioma tissues with high GSDMD expression had abundant macrophage cell (CD68+/CD163+ double positive) infiltration by using IF staining." (PMID 34830775, 2021). "High percentages of glioma patients with positive VAP-1/CD68 (65.75%) and VAP-1/CD163 (73.13%) co-immunoreactivity were apparently observed." (PMID 32349342, 2020). "A clear co-localization of C1q/CD68 immunoreactivity was detected in both low- and high-grade gliomas, thus identifying the macrophages infiltrating glioma tumor as the main source of local C1q synthesis and secretion." (PMID 31649675, 2019). "Using immunofluorescence, we confirmed the presence of tumor-infiltrating (CD68+) macrophages (indicated in red) in established gliomas (shown in green)." (PMID 31481662, 2019).
glioma (continued). "Antigens CD68, CD163, CD200, CD204, F4/80, and IBA-1 are among the most employed markers to identify glioma-associated microglia elements and macrophages (GAMs), while microglia can be distinguished from macrophages through their low expression of CD45." (PMID 29584702, 2018). "Due to the importance of GAMs in glioma progression, we also investigated Iba1 and CD68 cell immuno-reactivity." (PMID 30542347, 2018). "(c) Myeloid cell activation (CD68) and infiltration (F4/80) in glioma mass in mice treated with IL-15 or vehicle, as shown in (a), analyzed at the end of treatment (17 days after glioma transplantation)." (PMID 29286001, 2017). "Peptide R-treated gliomas showed a reduction of CD11b+ and CD68+ cells migrated at the tumor edge as compared with control and Plerixafor groups." (PMID 27015814, 2016). "We also co-stained sections of RMPAhigh or RMPAlow gliomas with CD31 (a marker for vessel endothelial cells) or CD68 (a marker for TAM) with antibody to p-ERK or p-AKT." (PMID 27385209, 2016). "It is worth noting that glioma cells express the CD68 marker, as confirmed by immunostaining of U87MG cells in vitro and as previously reported." (PMID 27015814, 2016). "BDNF infusion reduces M/Mφ infiltration and CD68 immunoreactivity in tumour mass and reduces glioma migration inhibiting the small G protein RhoA through the truncated TrkB.T1 receptor." (PMID 25818172, 2015). "BDNF has direct effects on tumour cells, reducing glioma cell migration in vitro and impairing the expression of the phagocytic marker CD68 on M/Mφ, and their infiltration in the tumour mass." (PMID 25818172, 2015). "The proportions of CD163+ macrophages among CD68+ reflect the proportion of macrophages polarized to M2 phenotype, which was correlated with the histological grade in gliomas, and these findings were in accordance with our present study." (PMID 24883329, 2014). "Recently, glioma cells CD68 expression has been assigned of prognostic value, especially for astrocytomas." (PMID 24376672, 2013). "In low grade gliomas the pan-macrophage marker CD68 was limited in scattered or perivascular and adjacent to neurons microglia/macrophages, as well as intravessel monocytes." (PMID 24376672, 2013). "They demonstrated that patients with gliomas that had high TIM-3 and CD68 expression using the median expression as a threshold displayed significantly lower survival compared to glioma patients who expressed either high TIM-3/low CD68, low TIM-3/high CD68, or low TIM-3/low CD68." (PMID 40072074, 2025). "A previous study investigated the role of CD68 in glioma at the transcriptome level." (PMID 38539537, 2024). "The number of macrophages expressing CD68 increases with the grade of glioma, which is often associated with a negative impact on survival prognosis." (PMID 39156969, 2024). "Additionally, immunohistochemical (IHC) analysis revealed that CD68, a macrophage marker, was significantly elevated in glioma tissues with high CLIC4 expression." (PMID 39595145, 2024). "CD68 has been extensively examined in glioma and recurrent GBM." (PMID 39409905, 2024). "Moreover, a large number of CD68-positive cells were detected in the surgically resected human glioma tissues of GBM patients, which was a sign of phagocytic activity of macrophages/microglia." (PMID 39156969, 2024). "However, in this regard, a study involving the IV infusion of oncolytic reovirus against high-grade gliomas showed evidence of an increased infiltration of CTLs and CD68+ macrophages/microglia as well as an upregulation of IFN-regulated gene expression." (PMID 37046685, 2023). "In addition, flow cytometry analysis presented that when cocultured with DHX9‐overexpressed glioma cells, the ratio of CD68+/CD163+ cells were significantly higher than the control." (PMID 36377508, 2023). "GAMs (CD68+) were isolated from glioma samples and cultured to obtain conditioned media." (PMID 36969175, 2023).
glioma (continued). "Furthermore, we showed that CSF-1R inhibition significantly reduced the number of GAMMs infiltrating the glioma tissue, identified as CD68+ cells, and the inhibitory effect was detected also after brain repopulation." (PMID 35115369, 2022). "Subsequently, we further evaluated the representative glioma‐associated microglia/macrophage (GAM)‐related genes expression level between high‐ and low‐risk group, higher expression level of IBA1, TMEM119, CD68, CSF1R, and TGFB1 was found in the high‐risk group." (PMID 35985661, 2022). "Furthermore, immunohistochemistry demonstrated that PD-L2 and the macrophage biomarker CD68 were both increased in glioma, with PD-L2 expression having a strong positive connection with CD68 expression." (PMID 35756621, 2022). "However, the third patient who had a prolonged survival showed a clearly reduced number of CD68+ macrophages in the specimen and also a lower proliferation of glioma cells." (PMID 34998092, 2022). "We observed that in GEMM of gliomas, oncostreams are formed by GFP+ tumor cells, and are enriched in other tumor microenvironment cells such as ACTA2+ mesenchymal cells, IBA1+, and CD68+ tumor associated microglia/macrophages cells, Nestin+ cells and GFAP+ glial derived cells." (PMID 35750880, 2022). "Abundant TAM (CD68+/CD163+) infiltration was observed in glioma tissues with high GSDMD expression." (PMID 35990696, 2022). "High levels of CD68 in tumor samples correlated with an adverse prognosis in glioblastoma, kidney renal clear cell carcinoma, lower-grade glioma, liver hepatocellular carcinoma, lung squamous cell carcinoma, thyroid carcinoma, and thymoma and a favorable prognosis in kidney chromophobe." (PMID 35550532, 2022). "Moreover, we showed that there is a strongly positive correlation between SPP1 and CD68 expression levels in glioma samples, Similarly, positive correlation between VIM and CD68 expression levels in glioma samples was observed." (PMID 34805184, 2021). "Additionally, immunohistochemistry revealed that PDIA5 and macrophage biomarker CD68 were upregulated in high-grade gliomas, and patients with low PDIA5 level experienced favorable outcomes among 33 glioma patients." (PMID 33664747, 2021). "Consequently, we detected macrophage biomarker CD68 in gliomas and normal brain tissue samples from Xiangya Hospital using IHC staining and found that the number of CD68 positive cells was positively correlated with the WHO grade of gliomas." (PMID 33664747, 2021). "Moreover, a positive relationship was observed in correlation analysis between PDIA5 and CD68 in gliomas patients from TCGA dataset." (PMID 33664747, 2021). "Immunocytochemical staining of dissociated gliomas revealed GFAP-carrying (GFAP+) CD68+ cells." (PMID 33501422, 2021). "Although VAP-1/CD68 and VAP-1/iNOS also exhibited their diagnostic properties for overall survival, they did not exhibit the same degree of diagnostic accuracy in gliomas as that of VAP-1/CD163 (VAP-1/CD68, AUC = 0.7300; VAP-1/iNOS, AUC = 0.5535)." (PMID 32349342, 2020). "Increased numbers of CD68+ and higher ratio of CD163/AIF+ cells, as TAMs markers, and more FOXP3+ cells were associated with shorter progression-free survival, while high CD3+ and CD8+ T cells accompanied by low CD68+ and high IDO+ cell counts were associated with better glioma prognosis." (PMID 33050070, 2020). "Characteristic surface markers of tumor-associated macrophages, like CD11b and CD68, were found in gliomas of both mouse strains, without noticeable differences in expression." (PMID 32668709, 2020). "VAP-1/CD68 denoted acceptable accuracy for glioma prognosis (AUC = 0.7300)." (PMID 32349342, 2020). "CD68 is considered a macrophage marker that in gliomas is mainly derived from M2 macrophages." (PMID 31701625, 2020). "Moreover, it also demonstrated that positive VAP-1/TAM markers co-immunoreactivities yielded poorer prognosis for glioma patients (VAP-1/CD68, p < 0.0001; VAP-1/iNOS, p = 0.0113; VAP-1/CD163, p < 0.0001)." (PMID 32349342, 2020).